LGALS3 (galectin 3)
Diseases named in the same sentence as LGALS3 in open-access papers (continued):
Sharing a sentence is not in itself a finding about the gene and the disease.
tumor (continued). "This suggests that gold(III) porphyrin might significantly enhance its concentration and delivery to cancer cells by binding to human galectin-3 that keeps its orientation towards tumor associated carbohydrate antigens." (PMID 31842510, 2019). "Similarly, increased galectin 3 expression has been associated with a more favourable prognosis in several tumour types." (PMID 29386018, 2018). "Our results clearly demonstrate that an interruption of O-glycans extension caused by ST6GalNAc-I enzymatic activity leads to tumor cells resistance to chemotherapeutic drugs, highlighting the need for the development of novel strategies to target galectin-3 and/or ST6GalNAc-I." (PMID 27835877, 2016). "In a galectin-3 rich milieu (e.g., a tumor), reduced motility of galectin-3 cross-linked glycoproteins on activated infiltrating CTLs could explain the decreased CTL activity within tumors." (PMID 26136747, 2015). "Galectin-3 was thus predominantly expressed by type 2 macrophages, suggesting that tumor infiltrating cells expressing galectin-3 might be associated with a tumor promoting microenvironment." (PMID 26066796, 2015). "Interestingly, the presence of galectin-3 in tumor-associated stroma was related to unfavorable prognosis." (PMID 24982845, 2014). "Here, we have analyzed the impact of heterologous xenogenic expression of galectin-3 in Tm1 cells engrafted in both wild-type and galectin-3 null mice to address the role of galectin-3, and its cellular origin, in melanoma tumor growth and tumor-associated angiogenesis." (PMID 24421272, 2014). "Galectin-3 (Gal-3), a member of galectins family, is a multifunctional protein which is implicated in various biological processes including cell proliferation, apoptosis, angiogenesis, tumor progression and metastasis." (PMID 24639736, 2013). "The data presented above suggest that the detection of increased galectin-3 levels in the serum of certain patients with cancer may reflect biological aspects of tumor behavior associated with enzymatic activity of certain enzymes (PSA, MMPs, c-Abl, PTEN)." (PMID 23625538, 2013). "Experimental data available today demonstrate an association between galectin-3 levels (up-regulation as well as down-regulation) and numerous pathological conditions such as heart failure, infection with microorganisms, diabetes, and tumor progression." (PMID 23625538, 2013). "In addition, the increased expression of galectin-1 and/or galectin-3 has been reported to be associated with tumour progression." (PMID 23799140, 2013). "Galectin-3 has several described associations and roles related to cancer, in particular in relation to cell-cell and cell-matrix interactions, metastasis, angiogenesis, tumour progression and resistance to apoptosis/anoikis." (PMID 23285151, 2012). "The association of endothelial galectin-3 with α3β1 integrin on the tumor cells then stabilizes this adhesion and may mediate multiple downstream signals that determine the fate of the cell deposit and organ-specific metastasis." (PMID 22272201, 2012). "Thus, an increase of tumour cell aggregation as a result of the increased interaction between circulating galectin-3 and cancer-associated MUC1 in cancer patients provides a survival advantage to the disseminating tumour cells in the circulation." (PMID 20565834, 2010). "Treatment with WEB2170 alone or associated with DTIC also modified the tumour microenvironment by reducing the number of intra-tumoural blood vessels and tumour infiltration by macrophages/dendritic cells expressing galectin-3, a molecule that is associated with the suppressive M2 phenotype." (PMID 20465821, 2010). "Taken together, human tumour cell lines frequently express highly glycosylated C4.4A, which obviously can prevent binding of the antibodies generated by peptide vaccination and can also interfere with the association of galectin-3 with C4.4A." (PMID 17912244, 2007).
tumor (continued). "Furthermore, we found that decreased OPN expression was associated with lower galectin-3 and enolase two protein levels in the primary tumor-derived transfected cell line; however, the expression of these proteins was increased in the metastatic cell line after OPN silencing." (PMID 34257527, 2021). "Tumor–stromal cells (e.g., endothelial cells, immune and inflammatory cells, cancer-associated fibroblasts, myofibroblasts, and mesenchymal stromal cells) behavior is affected by extracellular galectin-3 and these cells are also capable of secreting this molecule." (PMID 24982845, 2014). "However, tumor growth was significantly delayed in galectin-3 deficient mice." (PMID 24421272, 2014). "Among them, Galectin-1, Galectin-3, and Galectin-9 have been most extensively investigated for their multifaceted roles in shaping the tumor microenvironment." (PMID 42129932, 2026). "Galectin-3 (Gal-3) has emerged as a central node in PCa pathobiology, influencing tumor survival, metastasis, and immune escape." (PMID 42187597, 2026). "Recent studies have highlighted the significance of Galectin-3 in cancer as an intrinsic tumor escape mechanism." (PMID 41477833, 2026). "Researchers have proposed Tmem119 as a marker for microglia during CNS inflammation following nerve injury, while Galectin-3 (Gal-3) serves as a critical marker for macrophages engaged in tumor immunosuppression." (PMID 39857798, 2025). "Galectin-3 (Gal-3)is a galactose-binding lectin involved in pathologiessuch as inflammation, fibrosis, heart disease, and tumor progression.Here, we report N-aryl-N-(thio)­lactosylamidesas a novel class of Gal-3 inhibitors." (PMID 41217252, 2025). "Second, we discovered that all sEV subtypes derived from two distinct tumor cell types were internalized via clathrin-independent endocytosis mediated by galectin-3 and LAMP-2C, whereas some sEV subtypes were internalized through caveolae." (PMID 40075063, 2025). "Galectin-3 plays a key role in tumor progression and metastasis through c-MYC upregulation and YAP1/RalA/RalBP, conferring an aggressive phenotype." (PMID 40149589, 2025). "For example, interactions have been observed between platelet GPVI and tumor galectin-3, platelet integrin α6β1 and tumor ADAM9, platelet CLEC-2 and tumor podoplanin, and platelet GPIIb/IIIa and tumor ανβ3." (PMID 39934930, 2025). "Together, these results indicate that K2 and L2 can significantly inhibit galectin-3-mediated tumour cell adhesion." (PMID 41023585, 2025). "Having shown a potent effect of K2 on inhibition of galectin-3-mediated tumour growth and metastasis in the chick embryos, its effect on tumour growth and metastasis was further investigated in mice." (PMID 41023585, 2025). "It increases T antigen expression and Galectin-3+ macrophage recruitment, which supports tumor invasion and immune suppression." (PMID 40718829, 2025). "At the beginning of this study, through immunohistochemical and bioinformatics analyses, we discovered that LGALS3+ tumor cells were highly correlated with fibroblasts via the PPIA-BSG pathway." (PMID 40600063, 2025). "Galectin-3 (Gal-3) was found to bind to core 1 mucin-type glycans (TF antigen) and elicit an immunosuppressive response in tumor-expressing environments." (PMID 40363702, 2025). "Administration of K2 significantly reduced galectin-3 mediated tumour growth and metastasis in vivo in chick embryo and in mice." (PMID 41023585, 2025). "Binding of galectin-3 to cell surface glycans also promotes the formation of an inflammatory and fibrotic environment within the tumour that supports tumour growth and resistance to cancer therapeutic treatments including chemo-, radio-, and immune-therapies." (PMID 41023585, 2025). "Functionally, galectin-3 binds to multiple sites along poly-LacNAc chains on the tumor cell surface, effectively shielding tumor cells from immune recognition and destruction by natural killer (NK) cells." (PMID 40252176, 2025).
tumor (continued). "For therapeutic targeting investigation, GM-CT-01 (a galactomannan) and modified citrus pectin (MCP) block galectin-3 carbohydrate-binding domains, showing preclinical efficacy in reducing tumor growth and metastasis." (PMID 40600063, 2025). "By inhibiting galectin-3, pectin can reduce tumor growth, suppress metastasis and inhibit tumor cell proliferation." (PMID 41249064, 2025). "Analyses of bulk RNA-seq of human ccRCC revealed that PDCD1LG2 and CD80 expression were upregulated in ccRCC tumours compared to normal kidney, as was expression of LGALS3, LGALS9, SELL and CD276." (PMID 40473819, 2025). "Together, these results demonstrated the effectiveness of these novel galectin-3 inhibitors on inhibition of galectin-3-mediated tumour growth and metastasis in vivo." (PMID 41023585, 2025). "Along with the acquisition of single-cell RNA-sequencing data, the relationship of each clustering target, CCL2-positive fibroblasts, focused on the PPIA-BSG pathway, which plays a critical role in connecting LGALS3-high tumor cells." (PMID 40600063, 2025). "Galectin-3 is known to promote tumour cell adhesion to and invasion through basement matrix in tumour cell breakout at the primary tumour site by interaction with a number of basement matrix glycoproteins such as laminin." (PMID 41023585, 2025). "Background/Objectives: Galectin-3 (Gal-3), encoded by LGALS3, is a β-galactoside-binding lectin involved in diverse tumor-associated processes, including immune modulation, cell cycle regulation, and stress adaptation." (PMID 41153387, 2025). "Based on human single-cell data from BCBM and liver metastases, alternative immune checkpoints such as LAG3–galectin-3 are highly active in tumor and infiltrating cells, suggesting their potential as important complements to PD-1/PD-L1 inhibitors." (PMID 41219968, 2025). "LGALS3 promoted tumor progression, invasiveness, and immune suppression, and blocking LGALS3‐ANXA2 has been documented to initiate cell apoptosis by suppressing all downstream EGFR signaling pathways." (PMID 40776410, 2025). "For instance, polysaccharides have been shown to target metabolic enzymes such as an α-D-glucan binding to ALDOA or other functional proteins such as safflower polysaccharide HH-1 targeting galectin-3 to inhibit tumor growth." (PMID 41451369, 2025). "Having revealed significant effects of the compounds on galectin-3-mediated cancer cell activities in vitro, K2 was selected and investigated on its effect on tumour growth and metastasis in chick embryos." (PMID 41023585, 2025). "The effectiveness of these galectin-3 inhibitors on tumour growth and metastasis were further demonstrated in mice." (PMID 41023585, 2025). "In the hypoxic Pseudo.A region, ITGA5 and SDC4 showed enhanced abundance in subtype 2 TCs in comparison to CLEC5A which was enriched in tumor infiltrating MG/MØs, and LGALS3 that was overall higher in both TCs and surrounding stromal cell types." (PMID 41366031, 2025). "Homologous targeting of tumor cells is dependent on interactions with T antigen and beta-galactosid-binding proteins and galectin-3, as well as adhesion proteins on the surface of tumor cell membranes." (PMID 40270890, 2025). "When K2 was injected to the allantoic cavity of embryos, the embryos that formed tumours of SW620 group reduced to 30% (3/10) while the embryos of the galectin-3 knockdown SW620 group was seen to be more than doubled (67%, 7/10)." (PMID 41023585, 2025). "While matrisome transcripts like ITGA5 and LGALS3 were enriched in TCs and infiltrating stromal cells residing around necrotic regions, the hypoxic tumor regions revealed enhanced expression of IGFBP2 and COL20A1." (PMID 41366031, 2025). "For example, binding of galectin-3 to integrins or laminin enhances tumour cell adhesion and subsequent invasion into the surrounding tissues at the primary tumour sites." (PMID 41023585, 2025).
tumor (continued). "Increased level of galectin-3 has been reported to promote EMT in several cell types following active stimulation or in tumor biology via enhanced pAKT, pERK1/2, or β-catenin signaling." (PMID 40806748, 2025). "The results showed that TREM2f/f-Lyz2-Cre mice exhibited reduced tumor volumes and weights, slower tumor growth, and the combination therapy with the galectin-3 inhibitor GB1107 significantly decreased the tumor burden." (PMID 39135069, 2024). "Most studies in the literature report that galectin-3 expression is increased in invasive tumor cells." (PMID 39451592, 2024). "In the ARSB-treated tumor tissue, free galectin-3 and nuclear Sp1 declined, compared to the control." (PMID 37813168, 2024). "Subsequently, hsa-miR-27b-3p was determined as a prospective upstream tumor suppressive miRNA of LGALS3 according to correlation and expression analysis." (PMID 38643145, 2024). "First, in a cohort of early‐stage LUAD patients from HGUV we found that those patients with high FOXP3+ infiltration in tumor had high expression of LGALS3 in tumor." (PMID 37567864, 2024). "In this study, EMT was assessed immunohistochemically through changes in E-cadherin and vimentin expression in invasive tumor regions, and the expression of galectin-3 was investigated in these areas." (PMID 39451592, 2024). "LGALS3 expression showed a significant positive association with CD274, TIGIT, PDCD1, HAVCR2, CTLA4, LAG3, as well as PDCD1LG2 after adjustment for tumor purity in HCC." (PMID 38643145, 2024). "Tumor-educated TREM2+ macrophages are converted into M2-like TAMs by interacting with the novel ligand galectin-3 enriched in the TME." (PMID 39135069, 2024). "In melanoma CCDC50 is upregulated and the galectin-3/CCDC50-mediated lysophagy mechanism supports tumour growth and, potentially, also works in other tumours." (PMID 38990375, 2024). "Due to its ability to finely modulate immune response in vivo, Galectin-3 is a potential target molecule to be considered for overcoming tumor immune escape." (PMID 38317202, 2024). "Two potential ligands have been identified for LAG-3, which are present in the tumor microenvironment: liver sinusoidal endothelial cell lectin (LSECtin) and galectin-3 (Gal-3)." (PMID 39125946, 2024). "Proteins (e.g., carcinoembryonic antigen and galectin-3) on CCM can mediate adhesion to promote Au@c-CCM targeting tumor, and NPs lead to photothermal-mediated immunogenic death of tumor cells under NIR radiation." (PMID 39296987, 2024). "In this study, we have investigated how the presence of Galectin-3 in high-grade serous carcinoma (HGSC) affects the immune-mediated anti-tumor response." (PMID 39759523, 2024). "Investigating the correlation between LGALS3 and immune cells has the potential to improve immunotherapy and tumor treatment." (PMID 38643145, 2024). "Galectin-3 promotes tumor growth by inhibiting phagocytosis, macrophage re-polarization and T-cell immune responses." (PMID 39135069, 2024). "Galectin-3 plays crucial roles in cancer, including promotion of tumor cell survival, angiogenesis, tumor transformation, tumor progression and metastasis." (PMID 39135069, 2024). "One potential mechanism involves the secretion of galectin-3, a molecule that binds to mature tumor-specific T cells within the tumor microenvironment, inducing apoptosis in these T cells." (PMID 38732975, 2024). "The knockdown of galectin-3 has been shown to decrease tumor initiation, aggressiveness, and chemoresistance to cisplatin and paclitaxel in lung adenocarcinoma." (PMID 38539500, 2024). "Modified citrus pectin is a carbohydrate-based galectin-3 inhibitor that has also shown antimetastatic properties as well as promise in inhibiting tumor growth and restoring T-cell surveillance." (PMID 38927753, 2024). "Using functional NK cell anti-tumor assays, we investigated how Galectin-3-induced ROS release from neutrophils impacted on NK cell functionality." (PMID 39759523, 2024).
tumor (continued). "Galectin-3 is a pleiotropic tumor relevant molecule, which deserves particular attention in immuno-oncology." (PMID 38317202, 2024). "T‐antigen has been demonstrated to bind circulating galectin‐3 (Gal‐3), thereby inducing cancer cell polarization, so that the cell adhesion molecules exposed enhance tumor cell homotypic aggregation and prevent anoikis." (PMID 38721992, 2024). "According to the TGCA human database, higher expression levels of LGALS3 are observed in HCC tumor tissues than in non-tumor tissues, and the expression levels are positively correlated with the stages of HCC." (PMID 38793619, 2024). "Using patient samples from two cohorts of chemo naïve patients diagnosed with HGSC, we detected high levels of Galectin-3 in the tumor metastatic environment of ascites." (PMID 39759523, 2024). "Galectin-3 plays a crucial role in enhancing the invasive capabilities of tumor cells by promoting the disruption of the basement membrane through the upregulation of matrix metalloproteinase activity." (PMID 39451592, 2024). "Previous studies suggested that LGALS3 abnormal expression throughout cancer progression promotes tumor growth, invasiveness, metastasis, as well as immune suppression." (PMID 38643145, 2024). "LGALS3 has been established to have a crucial function in glycolysis and contributes to tumor metabolic reprogramming to adapt to oxygen and nutrient deprivation in TME." (PMID 38643145, 2024). "Studies have shown that M1 polarization in CRC promotes the expression of galectin-3, enhancing macrophage infiltration and sensitizing immune responses against tumor cells." (PMID 38802814, 2024). "Our findings indicated that the upregulation of LGALS3 via the HCP5/hsa-miR-27b-3p axis is associated with unfavorable prognosis and increased tumor immune infiltration in HCC." (PMID 38643145, 2024). "Our results demonstrated a Galectin-3 mediated decrease of NK cell viability via neutrophil ROS release, with anti-tumor responses impeded by ROS." (PMID 39759523, 2024). "A cluster of expanded γδ T cells with high expression of Galectin-3 and other IL-17 associated genes was also recently found in human CRC tumours using single-cell RNA sequencing." (PMID 38953978, 2024). "In general, galectin-3 within the tumor micro-environment is considered to contribute to immunosuppression." (PMID 38990363, 2024). "In co-cultures with NK cells and K562 target cells, we observed that Galectin-3-induced production of reactive oxygen species in neutrophils resulted in decreased NK cell viability and lowered anti-tumor responses." (PMID 39759523, 2024). "This study sheds light on the intricate immune cell interactions within the tumor microenvironment in OC and suggests further investigation to evaluate Galectin-3 as a potential immunotherapeutic target in OC." (PMID 39759523, 2024). "The role of endothelial galectin-3 in tumor immunomodulation is still not fully understood but it appears that this family member acts somewhat more ambiguous as compared to galectin-1." (PMID 38990363, 2024). "Subsequently, in HCC, a correlation analysis was investigated between LGALS3 and tumor immunity-related indicators involving cell chemotaxis, immune checkpoints, immune cell biomarkers, and infiltration." (PMID 38643145, 2024). "Functionally, the galectin-3 inhibitor GB1107 alleviated the inhibitory effect of tumor cell-CM on TREM2-mediated phagocytosis." (PMID 39135069, 2024). "Analysis of the transcriptomic data revealed that LGALS3 (an important regulator of the tumour microenvironment 28-30), which is a target gene of the transcription factor JUN, was the most significantly decreased gene following HDAC7 knockdown." (PMID 39629136, 2024). "In models of breast and pancreas cancer, galectin-3 was shown to trigger endothelial cell functionality in vitro and stimulate tumor angiogenesis in vivo." (PMID 38990363, 2024).